CKS2 (CDC28 protein kinase regulatory subunit 2)
Diseases named in the same sentence as CKS2 in open-access papers (continued):
Sharing a sentence is not in itself a finding about the gene and the disease.
lung adenocarcinoma (7 papers, 2020 to 2024). A carcinoma that arises from the lung and is characterized by the presence of malignant glandular epithelial cells. "The survival and disease-free survival rates of lung adenocarcinomas with higher CKS2 expression are significantly lower than those of lung adenocarcinomas with lower CKS2 expression." (PMID 39188686, 2024). "In a study on lung adenocarcinoma, it was found that CKS2 expression affected the sensitivity of lung adenocarcinoma cells to carboplatin and paclitaxel, and the higher CKS2 expression, the higher the sensitivity of paclitaxel." (PMID 39188686, 2024). "To this end, we analyzed the correlation between CKS2 and MKI67 and PCNA, which were involved in the proliferation of lung adenocarcinoma cells, and found that CKS2 was significantly positively correlated with both of the genes." (PMID 36010686, 2022). "The upregulation of CKS2 in lung adenocarcinoma was related to worse survival of patients and larger tumor size." (PMID 35935749, 2022). "Additionally, we investigated in depth the expression of CKS2 in various histological subtypes of invasive lung adenocarcinoma and identified the roles of CKS2 in affecting the drug sensitivity of LUAD tumor cells to carboplatin and paclitaxel." (PMID 36010686, 2022). "However, the role of CKS2 in lung adenocarcinoma (LUAD) remains unkonwn." (PMID 34729099, 2021).
bladder cancer (6 papers, 2010 to 2024). "There is accumulating evidence that CKS2 is elevated in various cancer types, including colorectal, prostate, and bladder cancers." (PMID 31781310, 2019). "Our results, obtained from a sample set particularly rich of exfoliated cells, provide further molecular evidence on the involvement of hTR, hTERT and CKS2 gene expression in bladder cancer (BC) carcinogenesis." (PMID 20920335, 2010).
glioma (6 papers, 2021 to 2024). A benign or malignant brain and spinal cord tumor that arises from glial cells (astrocytes, oligodendrocytes, ependymal cells). "Multivariate analysis of TCGA and CGGA data indicated that increased CKS2 expression was an independent risk factor for overall survival and prognosis in glioma patients." (PMID 39188686, 2024). "Then, we further reviewed the clinical characteristics of 80 patients with glioma and explore the association between CKS2 expression and the clinicopathological features via immunohistochemistry assay." (PMID 36284444, 2023). "Multivariate data analysis from TCGA and CGGA indicated that increased expression of CKS2 was an independent risk factor for the prognosis of overall survival in glioma patients." (PMID 35663965, 2022). "CKS2 is also associated with the pathological stage of glioma, IDH mutation, 1p/19q co-deletion, and patient age." (PMID 35663965, 2022). "Although this study proposes an association between CKS2 and glioma and increases our overall knowledge of the role of CKS2 in glioma, some limitations remain." (PMID 35663965, 2022). "Univariate and multivariate Cox regression revealed that CKS2 was an independent risk factor for glioma." (PMID 35663965, 2022). "In addition, Kaplan-Meier survival analysis and Cox regression analysis showed that CKS2 was independently associated with poor prognosis in glioma patients." (PMID 39188686, 2024). "CKS2 expression is abnormally elevated in gliomas accompanied by peripheral diffusion and infiltration, and CKS2 overexpression is associated with the proliferation, invasion and migration of glioma cells as well as the shortened survival time of glioma patients." (PMID 39188686, 2024). "For glioma, CKS2 expression is a good diagnostic marker, with an AUC as high as 0.941." (PMID 35663965, 2022). "CKS2 methylation was also associated with poor prognosis in glioma." (PMID 35663965, 2022). "Although CKS2 is overexpressed in various cancers and results in poor prognosis, the specific underlying mechanism and potential role remain unclear, particularly in glioma." (PMID 35663965, 2022). "CKS2 acts as an oncogene in glioma to promote cell proliferation, invasion and epithelial-mesenchymal transformation pathway, while CKS2 knockdown can inhibit the proliferation, invasion and epithelial-mesenchymal transformation of glioma cell lines." (PMID 39188686, 2024). "To further understand the functions of CKS2 in gliomagenesis, we explore the effect of CKS2 on glioma cell migration and invasion." (PMID 36284444, 2023). "Compared with low‐grade glioma tissues, high‐grade glioma with CKS2 overexpression showed obvious activation of TGFβ/SMAD signaling." (PMID 36284444, 2023). "To provide further insights into the mechanisms of CKS2‐induced proliferation, we used GSEA to investigate the possible biological functional of CKS2 in glioma with GEO public dataset." (PMID 36284444, 2023). "qRT‐PCR, western blotting (WB), and immunohistochemistry (IHC) assays were used to investigate the expression patterns of CKS2 among glioma and brain tissues." (PMID 36284444, 2023). "Taken together, CKS2 protein upregulation contributed to gliomagenesis and correlated with poor prognosis of glioma." (PMID 36284444, 2023). "In conclusion, our study reported that transcription factor CKS2 can promote glioma cell proliferation, invasion, and migration." (PMID 36284444, 2023). "To investigate the clinical significance of CKS2 in human glioma, we initially analyzed the RNA‐seq data using the GSE7696, GSE54004, GSE4290, and GSE16011 datasets." (PMID 36284444, 2023). "In our study, we found that both center and border of glioma exhibited aberrantly elevated level of CKS2." (PMID 36284444, 2023). "Collectively, these findings revealed that CKS2 knockdown inhibited glioma proliferation and induced apoptosis in glioma cells and both pro‐apoptotic and anti‐apoptotic genes were involved." (PMID 36284444, 2023).
glioma (continued). "Consistent with the findings in the RNA‐seq datasets, the results of qRT‐PCR and WB assays showed that CKS2 mRNA and proteins were significantly increased in glioma tissues compared to normal brain tissues." (PMID 36284444, 2023). "To further explore the roles of CKS2 in tumorigenesis of glioma, we predicted its potential functions via synergistic genes enrichment analysis and gene set enrichment analysis (GSEA)." (PMID 36284444, 2023). "In this study, we confirmed that a significant increase of CKS2 in glioma patients with CKS2 overexpression implied shorter overall survival time." (PMID 36284444, 2023). "In colony formation assay, overexpressing endogenous CKS2 significantly increased the viability of the glioma cells, which formed bigger and more clones." (PMID 36284444, 2023). "In Transwell assay, findings showed that glioma cells had attenuated invasion ability following transfection with CKS2‐siRNA, whereas the capability was increased after being transfected with CKS2 overexpression vector in U251 and LN229 (p < 0.05)." (PMID 36284444, 2023). "Secondly, we verified that knockdown of CKS2 both sharply inhibited migration, invasion and induced apoptosis in glioma cells." (PMID 36284444, 2023). "To further validate the prognostic value of CKS2 mRNA expression in gliomas, we used RNA-seq data and survival data from 811 patients in the CGGA database." (PMID 35663965, 2022). "We employed cBioPortal to investigate the association between CKS2 mRNA expression in the CNV and methylation data in glioma samples." (PMID 35663965, 2022). "Demographic and clinical characteristics of patients with glioma with low and high expression of CKS2 in TCGA (n = 670)." (PMID 35663965, 2022). "To further explore the role of CKS2 in early-stage glioma, we utilized ssGSEA to research the connection between CKS2 mRNA expression levels and immune cell infiltration." (PMID 35663965, 2022). "CKS2 also plays an important role in tumor immunity and affects the tumor microenvironment, indirectly influencing the prognosis of patients with glioma and paving the way for becoming a potential immunotherapy target in the future." (PMID 35663965, 2022). "To further clarify the role of CKS2 in glioma immunity, we assessed the co-expression of CKS2 with MHC, immune activation, immunosuppression, chemokine receptors, and chemokines." (PMID 35663965, 2022). "To further verify the effect of CKS2 methylation levels in glioma, we scrutinized data from the CGGA database and found that higher WHO grades were associated with lower CKS2 methylation." (PMID 35663965, 2022). "To examine the potential mechanism by which CKS2 promotes tumor development, we divided glioma samples into high– and low–CKS2 expression groups." (PMID 35663965, 2022). "As expected, in vitro experiments strongly demonstrated that high CKS2 expression facilitates the proliferation and invasion of glioma cells." (PMID 35663965, 2022). "Compared with normal brain tissue, the expression of CKS2 was upregulated in glioma samples (p < 0.001)." (PMID 35663965, 2022). "In this analysis, we discovered that CKS2 was significantly overexpressed in glioma tissues, and this overexpression was correlated with the hypomethylation of CKS2." (PMID 35663965, 2022). "Cell viability, colony formation, and transwell assays were conducted to evaluate the influence of CKS2 on glioma cell proliferation and invasion." (PMID 35663965, 2022). "To research the role of CKS2 in glioma, we assessed the effect of CKS2 on glioma cell proliferation and migration." (PMID 35663965, 2022). "CKS2 was found in four glioma cell lines (HS683, U251, U87, and T98G) and was highly expressed in U251 and U87 cell lines." (PMID 35663965, 2022). "Univariate and multivariate analyses of this dataset also demonstrated that CKS2 mRNA expression was an independent prognostic factor (HR = 1.793; 95% CI: 1.473–2.184, p < 0.001) for glioma." (PMID 35663965, 2022).
glioma (continued). "qRT-PCR analysis revealed that CKS2 expression was remarkably upregulated in glioma tissue (n = 34) compared with normal brain tissue." (PMID 35663965, 2022). "Univariate and multivariate regression analyses identified CKS2 as an independent prognostic factor for glioma." (PMID 35663965, 2022). "Data from TCGA and GEO databases indicated that CKS2 is highly expressed in gliomas compared with normal brain tissue (p < 0.001)." (PMID 35663965, 2022). "This study demonstrates that CKS2 is a potential marker for glioma diagnosis and prognosis, highlights its role in proliferation and invasion, and shows its potential as an immunotherapy target." (PMID 35663965, 2022). "In addition, CKS2 activates the TGFβ/SMAD signaling pathway to promote EMT-like processes in gliomas, thereby inducing the aggressive and malignant phenotype of God cancer (epithelial-stromal transformation)." (PMID 39188686, 2024). "CKS2 is highly expressed in glioma compared to normal brain tissue." (PMID 39188686, 2024). "GSEA results showed that CKS2 might be involved in epithelial‐mesenchymal transition‐like (EMT) process in glioma." (PMID 36284444, 2023). "Besides, we also found that glioma cells with CKS2 overexpression tended to influence adhesion with adjacent cells and change cellular biological behaviors, such as migration and invasion." (PMID 36284444, 2023). "We identified CKS2 as a critical contributor to the gliomagenesis, which might provide a novel therapeutic target for inhibiting the spread and infiltration of glioma." (PMID 36284444, 2023). "The opposite trends were observed in glioma cells overexpressing CKS2 (p < 0.05)." (PMID 36284444, 2023). "Glioma cells were transfected with small interfering RNA/overexpression plasmid against CKS2, then clone formation assay, CCK‐8, wound healing, Transwell assay, and flow cytometry were performed to detect changes in cell viability, invasiveness, and the apoptosis rate." (PMID 36284444, 2023). "Moreover, we found that CKS2 inhibition induced a series of changes in EMT markers expression, which indicated that CKS2 participated in the regulation of EMT‐like malignant phenotype in glioma." (PMID 36284444, 2023). "In this study, Th2 cell levels were particularly elevated, whereas CD8+ T-cell levels were reduced, suggesting that CKS2 may help mediate immune escape in glioma." (PMID 35663965, 2022). "We also evaluated the relationship between CKS2 and a commonly used drug in glioma (cisplatin)." (PMID 35663965, 2022). "CKS2 is highly expressed in gliomas and results in a poor prognosis." (PMID 35663965, 2022). "In vitro experiments demonstrated that CKS2 might act as an oncogene in gliomas by affecting cell proliferation and invasion." (PMID 35663965, 2022). "In conclusion, CKS2 was overexpressed, whereas CKS2 methylation was decreased in gliomas." (PMID 35663965, 2022). "Cell proliferation and invasion tests enrich the functional role of CKS2 in gliomas." (PMID 35663965, 2022). "This indicates that patients with glioma with high CKS2 expression may better benefit from ICB treatment." (PMID 35663965, 2022). "CKS2 knockdown impeded the expansion and aggression of glioma cell lines." (PMID 35663965, 2022). "We also assessed CKS2 expression in glioma tissues and cell lines." (PMID 35663965, 2022). "Therefore, our study offers novel insights into the potential role of CKS2 in tumor pathogenesis and suggests its potential role as a biomarker in glioma." (PMID 35663965, 2022). "These clinical data further support the conclusion that CKS2 expression may be related to the degree of glioma malignancy." (PMID 35663965, 2022). "In addition, CKS2 may be a candidate prognostic biomarker for glioma and may predict survival in glioma patients." (PMID 39188686, 2024).
glioma (continued). "Consistently, glioma cells also exhibited enhanced migration capability in wound heal assay when treated with the CKS2 overexpression plasmid compared to the empty vector, while attenuated migration was observed following transfection with CKS2‐siRNA (p < 0.05)." (PMID 36284444, 2023). "At present study, we first reported that expression of CKS2 was aberrantly elevated in glioma with surrounding spread and infiltration, and CKS2 overexpression was related to proliferation, invasion, and migration of glioma cells and shorter survival time of glioma patients." (PMID 36284444, 2023). "We found that CKS2 overexpression correlates with poor prognosis in human glioma and knockdown of CKS2 could inhibit cell proliferation, migration, invasion, and induced apoptosis in glioma cells." (PMID 36284444, 2023). "Therefore, we investigate the effect of CKS2 on proliferation of glioma cells." (PMID 36284444, 2023). "In addition, CKS2 knockout inhibited proliferation and invasion of glioma cell lines." (PMID 35663965, 2022). "Therefore, the prognostic value and potential role of CKS2 in glioma require further investigation." (PMID 35663965, 2022). "Univariate and multivariate analyses reported that factors such as CKS2 expression level and WHO grade were significantly correlated with the prognosis of patients with glioma." (PMID 36284444, 2023). "Our experimental data and other studies above provide enough theoretical support and evidence for the molecular mechanism by which CKS2 induced EMT‐like process and tumorigenesis through activating TGFβ/SMAD signaling pathway in glioma." (PMID 36284444, 2023). "Furthermore, CKS2 promoted the EMT‐like process through TGFβ/SMAD signaling pathway in glioma, meanwhile, inhibition of TGFβ/SMAD could reverse the malignant phenotype caused by CKS2, which implied that CKS2 may serve as a potential target for the treatment of glioma." (PMID 36284444, 2023). "Knocking down CKS2 effectively inhibit the activation of TGFβ/SMAD signaling pathway and dramatically decrease glioma proliferation; the phenomenon above was also observed in glioma tissues." (PMID 36284444, 2023). "Among 80 patients with glioma in this study, the eight tissues of GBM patients that represented multifocal feature markedly expressed CKS2 in either the core or margin of tumor." (PMID 36284444, 2023). "This study used data from The Cancer Genome Atlas (TCGA) database to comprehensively evaluate the predictive worth of CKS2 mRNA expression, copy number variation (CNV), and methylation status in patients with glioma." (PMID 35663965, 2022). "Thus, CKS2 may have a role in proliferation and invasion in glioma." (PMID 35663965, 2022). "Additionally, CKS2, through activating TGFβ/SMAD signaling, promotes malignant phenotypes and the epithelial-mesenchymal transition process in glioma." (PMID 39548421, 2024). "In addition, CKS2‐mediated activation of TGFß/SMAD signaling pathway could induce aggressiveness and malignant phenotype (epithelial‐mesenchymal transition) in glioma." (PMID 36284444, 2023).
prostate carcinoma (5 papers, 2013 to 2024). A carcinoma that arises from epithelial cells of the prostate gland. "Therefore, we speculate that CCNA2 and CKS2 may be critical factors for the deterioration of prostate cancer, serving as new diagnostic biomarkers and therapeutic targets for CRPC." (PMID 37476415, 2023). "The TCGA database and GSE21032 verification found that highly expressed CKS2 plays a crucial role in the occurrence, development, recurrence, metastasis and progression of prostate cancer." (PMID 39188686, 2024). "The expression of CCNA2 and CKS2 in the training cohort CRPC samples was significantly higher than that in the primary prostate cancer samples (p < 0.001)." (PMID 37476415, 2023). "Through validation with training and testing cohorts, we found that CCNA2 and CKS2 significantly differed in expression levels between primary prostate cancer and CRPC." (PMID 37476415, 2023). "In prostate cancer, aberrant expression of CKS2 contributes to tumorigenesis by enhancing cell proliferation and inhibiting programmed cell death." (PMID 29760609, 2018). "The overexpression of cyclin kinase subunit 2 (CKS2) is tightly correlated with tumor aggressiveness and prognosis in various malignancies, including gastric, breast, liver and prostate cancer." (PMID 24137409, 2013). "Interestingly, previous studies found that CCNA2 and CKS2 were highly expressed in primary prostate cancer compared to normal prostate cancer tissues." (PMID 37476415, 2023). "Discussion: The expression of CCNA2 and CKS2 increases with the progression of prostate cancer, which may be one of the driving factors for the progression of prostate cancer and can serve as diagnostic biomarkers and therapeutic targets for CRPC." (PMID 37476415, 2023). "Prostate cancer is considered a continuous progressive disease, and as the disease progresses, CCNA2 and CKS2 increase." (PMID 37476415, 2023). "In our study, we further found that, compared with primary prostate cancer, the expression levels of CCNA2 and CKS2 in CRPC increased significantly." (PMID 37476415, 2023). "To determine our prediction, we found CCNB1, CKS2, MKI67, RRM2, TK1 and TOP2A acted as independent prognostic factors in TCGA prostate cancer." (PMID 32266115, 2020). "CKS2, TK1, MKI67, TOP2A, CCNB1 and RRM2 directly related to the recurrence and prognosis of prostate cancer." (PMID 32266115, 2020).
tongue squamous cell carcinoma (5 papers, 2021 to 2024). A squamous cell carcinoma that arises from the tongue. "In tongue squamous cell carcinoma, CKS2 promoted cell accumulation in G2/S phase and tumor progression via interacting with DUTPase and regulating its location in nucleus." (PMID 36284444, 2023). "In addition, as an important molecule regulating cell cycle, CKS2 promotes cell cycle progression in tongue squamous cell carcinoma through CCNB protein kinase binding, while silencing CKS2 can inhibit cell growth and cell cycle progression of cancer cells by inducing G2/M phase arrest." (PMID 39188686, 2024).